LTBP4 (latent transforming growth factor beta binding protein 4)
Description:
Key regulator of transforming growth factor beta (TGFB1, TGFB2 and TGFB3) that controls TGF-beta activation by maintaining it in a latent state during storage in extracellular space. Associates specifically via disulfide bonds with the Latency-associated peptide (LAP), which is the regulatory chain of TGF-beta, and regulates integrin-dependent activation of TGF-beta.
Synonyms: LTBP-4; LTBP-4L; FLJ46318; FLJ90018; ARCL1C; LTBP4L; LTBP4S
Tractability: Antibody: UniProt places it where antibodies can reach, with high confidence; its Gene Ontology location is reachable by antibodies, with high confidence; UniProt predicts a signal peptide or a membrane-spanning region. PROTAC: ubiquitination databases record sites on it.
Gene: Protein-coding gene on chromosome 19 (40,592,883 to 40,629,821, forward strand). Ensembl gene ENSG00000090006.
Subcellular location: Secreted, extracellular space, extracellular matrix
Pathways (Reactome):
Extracellular matrix organization: Molecules associated with elastic fibres
Signal Transduction: TGF-beta receptor signaling activates SMADs
Gene Ontology:
Molecular function: protein binding; transforming growth factor beta binding; calcium ion binding; extracellular matrix structural constituent; glycosaminoglycan binding; integrin binding; transforming growth factor beta receptor activity
Biological process: protein folding; regulation of cell growth; regulation of transforming growth factor beta receptor signaling pathway; cell surface receptor protein serine/threonine kinase signaling pathway
Cellular component: extracellular matrix; extracellular region; elastic fiber; microfibril; non-collagenous component of interstitial matrix; transforming growth factor beta complex
Genetic constraint (gnomAD): Loss-of-function variants: 95 observed, 153.54 expected, observed/expected ratio (o/e) 0.62, 90% interval 0.52 to 0.73. The upper end of that interval is the gene's LOEUF score, 0.73, which puts it in group 3 of 6, group 1 being the genes least tolerant of losing a copy. Missense variants: 2,116 observed, 2,116 expected, observed/expected ratio (o/e) 1, 90% interval 0.96 to 1.04. Synonymous variants: 947 observed, 867.65 expected, observed/expected ratio (o/e) 1.09, 90% interval 1.03 to 1.15.
Homologues: Orthologues: chimpanzee LTBP4 (96% identical), macaque LTBP4 (95% identical), pig LTBP4 (91% identical), dog LTBP4 (90% identical), mouse Ltbp4 (88% identical), rat Ltbp4 (88% identical), guinea pig LTBP4 (84% identical), tropical clawed frog ltbp4 (52% identical), zebrafish si:cabz01070274.1 (43% identical). Paralogues in human: LTBP2 (38% identical), LTBP1 (35% identical), LTBP3 (28% identical).
Diseases named in the same sentence as LTBP4 in open-access papers:
LTBP4 is named in the same sentence as 86 diseases in open-access papers, as found by Europe PMC text mining. Sharing a sentence is not in itself a finding about the gene and the disease. The quoted sentences say what the papers report.
muscular dystrophy (13 papers, 2012 to 2025). Muscular dystrophy (MD) refers to a group of more than 30 genetic diseases characterized by progressive weakness and degeneration of the skeletal muscles that control movement. "For example, upon Matr3 depletion we observed rearrangement within the Ltbp4-Tgfb1 locus, a region linked to muscular dystrophy in GWAS42–44." (PMID 38341433, 2024). "LTBP4 was identified as a genetic modifier of muscular dystrophy in mice where a polymorphism in the LTBP4 hinge region correlated with muscle membrane stability and fibrosis." (PMID 37746696, 2023). "LTBP4 was originally identified from a genome-wide search for genetic modifiers of muscular dystrophy in mice, where there are two different alleles." (PMID 34516828, 2021). "Although many genetic loci contribute to the DBA/2J background effect, DBA/2J mice feature the Ltbp4 risk allele, which is estimated to contribute to at least 40% of the variance of the muscular dystrophy phenotype in Sgcg mice." (PMID 29065150, 2017). "Genetic manipulation of Ltbp4 in dystrophic muscle also directly modulated sarcolemmal resealing, and Ltbp4 alleles acted in concert with Anxa6, a distinct modifier of muscular dystrophy." (PMID 29065150, 2017). "The gene for latent TGFβ binding protein 4 (LTBP4) was previously found to modify muscular dystrophy in both mice and humans with variants that confer protection from disease." (PMID 27148972, 2016). "An in-frame insertion polymorphism in the murine Ltbp4 gene associates with partial protection against muscular dystrophy." (PMID 27148972, 2016). "To assess the mechanisms by which LTBP4 acts in skeletal muscle and in muscular dystrophy, we generated transgenic mice overexpressing the protective allele of murine Ltbp4 using a promoter driving expression exclusively in skeletal muscle." (PMID 27148972, 2016). "In the setting of muscular dystrophy, the protective Ltbp4 allele was associated with increased grip strength, improved muscle membrane leak, and reduced fibrosis in the γ-sarcoglycan null (Sgcg) model of muscular dystrophy." (PMID 27148972, 2016). "Ltbp4 encodes latent TGFβ-binding protein 4, and TGFβ proteins have been extensively linked to fibrosis in many disease states including muscular dystrophy." (PMID 23216833, 2012). "Moreover, the LTBP4 gene identified in this study was confirmed to be associated with the clinical manifestations of muscular dystrophy in mice and humans." (PMID 35883386, 2022). "The rationale for this experiment was based on the growing body of literature linking LTBP4 function and stability to muscular dystrophy phenotype." (PMID 40309777, 2025). "Ltbp4 is the most abundant Ltbp in mouse skeletal muscle and is a modifier of disease in mouse models of muscular dystrophy and individuals with Duchenne muscular dystrophy." (PMID 40309777, 2025). "The activation of SMAD2/3 upregulates expression of ECM-associated genes, and the D2 strain carries an allele of Ltbp4 that enhances active TGF-β, contributing to the exacerbation of muscular dystrophy by the D2 background." (PMID 38175727, 2024). "Mouse models of muscular dystrophy in the D2 strain have markedly elevated TGF-β proteins, in part mediated by polymorphisms in the latent TGF-β binding protein 4 (Ltbp4) as well as a feedback loop with osteopontin (Spp1)." (PMID 38175727, 2024). "Ltbp4 was originally identified as a genetic modifier of mouse muscular dystrophy from an unbiased genome-wide search for modifiers." (PMID 34516828, 2021). "This mouse model has a more severe form of muscular dystrophy than the background-matched mdx mouse model because the human LTBP4 is more readily proteolyzed with increased TGFβ signaling." (PMID 34516828, 2021). "We now expressed LTBP4 protein in mature myofibers using a muscle specific promoter and found that overexpression of LTBP4 protein mitigates aspects of muscular dystrophy in the mdx mouse model." (PMID 27148972, 2016).
muscular dystrophy (continued). "To better understand LTBP4 and its role in modifying muscular dystrophy, we created transgenic mice overexpressing the protective murine allele of LTBP4 specifically in mature myofibers using the human skeletal actin promoter." (PMID 27148972, 2016). "We next evaluated the effect of LTBP4 skeletal muscle overexpression in the context of muscular dystrophy." (PMID 27148972, 2016). "LTBP4 is an extracellular matrix protein that was previously identified using an unbiased genomewide scan for modifiers of muscular dystrophy." (PMID 27148972, 2016). "A genomewide quantitative trait locus (QTL) screen in mice identified Ltbp4 as a genetic modifier of muscular dystrophy." (PMID 27148972, 2016). "In order to assess the effects of LTBP4 in muscular dystrophy, LTBP4 overexpressing mice were bred to mdx mice, a model of Duchenne muscular dystrophy." (PMID 27148972, 2016). "This study shows that LTBP4 modifies muscular dystrophy based on its ability to scaffold and regulate multiple TGFβ family members including myostatin." (PMID 27148972, 2016). "LTBP4 has been identified as an important genetic modifier of muscular dystrophy in mice and in boys with DMD." (PMID 26114882, 2015). "In addition, anti-LTBP4 therapy should be useful across other forms of muscular dystrophy, especially those that share similar pathology." (PMID 34516828, 2021). "Human genetic data also support a role for LTBP4 in human muscular dystrophy." (PMID 34516828, 2021). "In mice, the “risk” Ltbp4 allele encodes a shorter hinge region that is more susceptible to proteolysis, and this risk allele is found in the DBA/2J strain correlating with more severe muscular dystrophy." (PMID 29065150, 2017). "The LTBP4 modifier also correlates with differential outcomes in humans with muscular dystrophy." (PMID 29065150, 2017). "Interestingly, the effect of LTBP4 protein overexpression was enhanced in the setting of muscular dystrophy compared to what was seen in the wildtype background." (PMID 27148972, 2016). "The current study investigates the role of LTBP4 overexpression in a model of muscular dystrophy." (PMID 27148972, 2016). "LTBP4 overexpressing mice were bred with mdx mice, a mouse model of muscular dystrophy." (PMID 27148972, 2016). "LTBP4 was identified as a genetic modifier of muscular dystrophy in mice and humans." (PMID 27148972, 2016). "LTBP4 was previously shown to modify muscular dystrophy in humans and mice." (PMID 27148972, 2016). "Therefore, it was hypothesized that increased sequestration of TGFβ, mediated by higher levels of LTBP4 in TG+ mice, would result in a less severe form of muscular dystrophy." (PMID 27148972, 2016). "In addition, stabilization of the hinge region of Ltbp4 protein reduces TGF-β activation and mitigates the muscular dystrophy phenotype in some mouse models of muscular dystrophy." (PMID 40309777, 2025).
Duchenne muscular dystrophy (11 papers, 2016 to 2025). Duchenne muscular dystrophy (DMD) is a neuromuscular disease characterized by rapidly progressive muscle weakness and wasting due to degeneration of skeletal, smooth and cardiac muscle. "LTBP4 is also a genetic modifier of Duchenne muscular dystrophy (DMD), where polymorphisms in LTBP4 have been linked to the age at loss of ambulation in DMD patients." (PMID 35456902, 2022). "In humans, nonsynonymous single nucleotide polymorphisms in LTBP4 associate with prolonged ambulation in Duchenne muscular dystrophy." (PMID 27148972, 2016). "When this protective Ltbp4 allele was introduced into the mdx mouse model for Duchenne Muscular Dystrophy, these mice had significantly reduced fibrosis and increased strength." (PMID 27148972, 2016). "Overexpression of LTBP4 in a mouse model of Duchenne muscular dystrophy alleviated many disease-associated features producing larger muscles, increased strength, and reduced fibrosis in muscle." (PMID 27148972, 2016). "Complementing the studies in mice, non-synonymous single nucleotide polymorphisms (SNPs) in LTBP4 were associated with age at loss of ambulation in human Duchenne muscular dystrophy." (PMID 27148972, 2016). "In humans with Duchenne Muscular Dystrophy (DMD), LTBP4 genotype has been associated with prolonged ambulation in multiple cohorts." (PMID 26918958, 2016). "Currently, many of the studies on LTBP4 are focused on its role in Duchenne muscular dystrophy (DMD) and other hereditary diseases." (PMID 37960979, 2023). "Two genetic modifiers of Duchenne Muscular Dystrophy implicate the transforming growth factor β (TGFβ) pathway, osteopontin encoded by the SPP1 gene and latent TGFβ binding protein 4 (LTBP4)." (PMID 29065150, 2017). "Moreover, the anti-LTBP4 in combination with prednisone, a standard of care for Duchenne muscular dystrophy, further enhanced muscle function and protected against injury in mdx mice." (PMID 34516828, 2021). "In the recessive X-linked form of muscular dystrophy, Duchenne Muscular Dystrophy (DMD), it was recently found that the gene encoding the Latent Transforming Growth Factor-β Binding Protein 4 (LTBP4) whose function is to bind Transforming Growth Factor Beta (TGFβ), was indeed a modifier in DMD." (PMID 27695661, 2016). "In the search of genetic determinants of Duchenne muscular dystrophy (DMD) severity, LTBP4, a member of the latent TGF-β binding protein family, emerged as an important predictor of functional outcome trajectories in mice and humans." (PMID 34294164, 2021). "In summary, our data highlight SPP1 rs11730582 as a genetic modifier of the long-term effect of GCs treatment in Chinese patients with Duchenne muscular dystrophy, but do not indicate a previously reported association between LTBP4 haplotype and disease progression." (PMID 32849198, 2020).
pulmonary emphysema (11 papers, 2009 to 2025). A subcategory of chronic obstructive pulmonary disease (COPD). "Ltbp4 deficiency leads to pulmonary emphysema, cardiomyopathy, colorectal cancer, and profound defects in the elastic fiber structure of the ECM." (PMID 38389090, 2024). "In humans, mutations in LTBP4 result in autosomal recessive cutis laxa type 1C, characterized by redundant skin, pulmonary emphysema, and valvular heart disease." (PMID 34071145, 2021). "Identification of additional cases is needed to confirm the existence of a novel CRC predisposition syndrome driven by epigenetic inactivation of LTBP4, potentially also linked to other clinical phenotypes associated with LTBP4 deficiency, such as pulmonary emphysema." (PMID 41194282, 2025). "Autosomal recessive cutis laxa subtype C (ARCL1C) or Urban–Rifkin–Davis syndrome, caused by biallelic variants in the LTBP4 gene, is characterized by early childhood-onset pulmonary emphysema, peripheral pulmonary artery stenosis, inguinal hernias, and hollow-organ diverticula." (PMID 34071145, 2021). "The precise mechanism of how TGFβ pathways cause LTBP4-related emphysema remains unclear, although upregulated TGFβ signaling has been observed in Lbpt4−/− mouse embryos." (PMID 34071145, 2021). "Expression of LTBP4 is critical for the development and maintenance of lung architecture, LTBP4 variants are associated with impaired alveolarization and airway collapse, and LTBP4 null mice develop emphysema." (PMID 24498427, 2014). "Ltbp4−/− mice grew significantly slower than their WT littermates, developed dermal and cardiopulmonary abnormalities and died within 2 weeks after birth, most likely due to respiratory failure caused by extensive pulmonary emphysema similar to that observed in ARCL1C patients." (PMID 25713297, 2015). "Supporting the role of LTBP4 inactivation in CRC predisposition, Ltbp4 double knockout (KO) mice develop colorectal adenomas and carcinomas, along with severe pulmonary emphysema and cardiomyopathy." (PMID 41194282, 2025). "In addition to early-onset CRC, pulmonary emphysema—and possibly other phenotypes associated with LTBP4 deficiency—may also occur in individuals with monoallelic methylation of LTBP4 CpG island 102, potentially offering clues to the underlying constitutional epigenetic defect." (PMID 41194282, 2025). "In patients with LTBP4-related cutis laxa, emphysema is a dominant phenotype observed as congenital or early onset and can be progressive." (PMID 34071145, 2021). "Mutant mice generated by a gene trap integration into the mouse LTBP-4 gene developed severe pulmonary emphysema owing to a reduced deposition of TGF-β1 in the extracellular space." (PMID 28784933, 2017). "Based on proband main clinical signs (cutis laxa and pulmonary emphysema), clinical exome sequencing (CES) was performed and showed a new nine base-pairs homozygous in-frame deletion in LTBP4 gene." (PMID 35972031, 2022). "Furthermore, reduced angiogenesis, abnormal elastogenesis, altered profibrotic changes, increased myofibroblast counts, and enhanced TGFβ activity were observed in Lbpt4−/− lungs; thus, these factors may play a role in the pathophysiology of LTBP4-related pulmonary emphysema." (PMID 34071145, 2021).
cutis laxa (10 papers, 2015 to 2026). Cutis laxa (CL) is an inherited or acquired connective tissue disorder characterized by wrinkled, redundant and sagging inelastic skin associated with skeletal and developmental anomalies and, in some cases, with severe systemic involvement. "This marker is located in CYP2A6 as well as in an enhancer region of LTBP4, which is associated with cutis laxa." (PMID 40831500, 2025). "Furthermore, LTBP4 genetic mutations have been linked to various disorders, including cutis laxa, scleroderma, pulmonary, cardiac, and cancer." (PMID 38928268, 2024). "However, the pleiotropy of CYP2A6 and LTBP4 may be the molecular reason why tobacco smoking can lead to a rapid, severe loss of lung function in individuals with LTBP4-related cutis laxa." (PMID 40831500, 2025). "ATS should be differentiated from EFEMP2-related cutis laxa, Loeys-Dietz syndrome, Ehlers-Danlos syndrome, FBLN5-related cutis laxa, LTBP4-related cutis laxa and Occipital horn syndrome." (PMID 34384376, 2021). "Some other monogenetic lung disorder-related genes were enriched in specific SAE cell types, including BC (LTBP4, ELN, cutis laxa), ionoctyes (HPS5, Hermansky-Pudlak syndrome), mucin-producing cells (COL1A1, Ehlers-Danlos syndrome), and neuroendocrine cells (BMPR2, pulmonary hypertension)." (PMID 32727470, 2020).
autosomal recessive cutis laxa type 1C (9 papers, 2019 to 2022). "Biallelic alterations in latent transforming growth factor beta-binding protein 4 gene (LTBP4) cause autosomal recessive type 1C cutis laxa (ARCL1C, MIM #613177)." (PMID 35972031, 2022). "Mutations in LTBP4 are associated with an inherited connective tissue disease, autosomal recessive cutis laxa type 1C (ARCLIC) in humans, which is recapitulated by an ARCLIC-like phenotype in LTBP4 deficient mice." (PMID 35456902, 2022). "LTBP4 mutations are linked to autosomal recessive cutis laxa type 1C (ARCL1C), a rare congenital disease characterised by high mortality and severely disrupted connective tissues." (PMID 34539739, 2021). "LTBP4 is important in elastic fibre assembly with LTBP4 mutations resulting in Urban-Rifkin-Davis Syndrome (URDS) also known as autosomal recessive cutis laxa type 1C which is replicated in knockout mouse models." (PMID 31226403, 2019). "Mutations in both LTBP4 isoforms lead to autosomal recessive cutis laxa type 1C (ARCL1C), initially named Urban-Rifkin-Davis Syndrome, and an ARCL1C-like phenotype is seen in LTBP4 deficient mice." (PMID 34539739, 2021). "Autosomal recessive cutis laxa type IC (ARCL IC, MIM: #613177) results from a mutation in the LTBP4 gene (MIM: #604710) on chromosome 19q13." (PMID 33302946, 2020). "Humans with inactive LTBP-4 develop autosomal recessive cutis laxa type 1C (ARCL1C), characterised by severe craniofacial, developmental and potentially fatal pulmonary defects." (PMID 30016650, 2019).
cardiomyopathy (8 papers, 2015 to 2025). A disease of the heart muscle or myocardium proper. "A mouse model deficient in the short isoform of Ltbp4 displays early lethality from pulmonary fibrosis, cardiomyopathy and colon cancer, indicating the importance for regulating TGFβ in the heart and during development." (PMID 26918958, 2016). "Although deletion of Ltbp4 in the mouse suggests that LTBP4’s activity is important in the heart, LTBP4 SNPs had not previously been associated with cardiomyopathy in humans." (PMID 26918958, 2016). "The rs10880 T/T genotype in the LTBP4 gene, in LD with the IAAM haplotype, also showed a trend of association with delayed onset of cardiomyopathy, although not statistically significant." (PMID 26513582, 2015). "Furthermore, mice lacking the short isoform of Ltbp4 (Ltbp4S-/-) develop cardiomyopathy with biventricular dilatation." (PMID 26918958, 2016).